RUNX1 (RUNX family transcription factor 1)
Diseases named in the same sentence as RUNX1 in open-access papers (continued):
Sharing a sentence is not in itself a finding about the gene and the disease.
rhabdomyosarcoma (2 papers, 2012 to 2015). A rare aggressive malignant mesenchymal neoplasm arising from skeletal muscle. "While the C2C12 cell data supported an anti- differentiation function of Runx1 the human rhabdomyosarcoma cell data indicated that Runx1 promotes myoblast differentiation and that Runx1, MyoD and c-Jun cooperate to induce this differentiation." (PMID 26275053, 2015). "On the other hand, similar enhanced differentiation was observed upon forced expression of Runx1 in rhabdomyosarcoma cells." (PMID 26275053, 2015).
serous ovarian cancer (2 papers, 2022 to 2023). "Western blot analysis revealed RUNX1 overexpression in high-grade serous ovarian cancer cell lines (SKOV3 and OVCAR3), compared to human normal ovarian epithelial cells (IOSE80)." (PMID 38057816, 2023). "In addition, RUNX1 knockdown impaired cellular functions of high grade serous ovarian cancer cell." (PMID 38057816, 2023).
squamous cell carcinoma (2 papers, 2020 to 2022). A carcinoma arising from squamous epithelial cells. "Representative positive staining patterns of RUNX1 are shown in adenocarcinoma and squamous cell carcinoma." (PMID 32498288, 2020). "Reduced RUNX1 expression was not related to pathologic stage, but was found more frequently in woman and in adenocarcinoma and was significantly associated with poor overall survival in adenocarcinoma (p = 0.005) but not in squamous cell carcinoma (p = 0.87)." (PMID 32498288, 2020).
systemic sclerosis (2 papers, 2025). A chronic disorder, possibly autoimmune, marked by excessive production of collagen which results in hardening and thickening of body tissues. "Notably, RUNX1’s broader role in tissue remodeling is evident in fibrotic diseases like systemic sclerosis (SSc), where hypomethylation-driven RUNX1 overexpression accelerates ECM dysregulation." (PMID 40917776, 2025).
trisomy 21 (2 papers, 2022 to 2023). A chromosomal disorder consisting of the presence of an extra chromosome 21. "Trisomy 21 up-regulates GATA1s expression leading to aberrant megakaryopoiesis, and the overdosage of RUNX1, ETS2, and ERG accelerates production of aberrantly differentiated cells." (PMID 36035173, 2022). "It appears that SON, another HSA21 gene, inhibits RUNX1 expression, which may neutralize trisomy 21-related overdosage of RUNX1 effects." (PMID 36035173, 2022).
Trisomy 8 (2 papers, 2021 to 2023). "Trisomy 8 is frequently associated with mutations in driver genes including RUNX1, ASXL1, DNMT3A43, TET244, and IDH1 and IDH245." (PMID 34707142, 2021).
uterine cancer (2 papers, 2020 to 2022). Primary or metastatic malignant neoplasm involving the uterine corpus and/or the cervix. "In addition, deep deletion of RUNX1 occurred in 6.59% (12 cases) of patients with ESCA (182 cases), and mutations in RUNX1 were the primary alteration type in 4.91% (26 cases) of patients with uterine cancer (529 cases)." (PMID 35534796, 2022).
uveal melanoma (2 papers, 2018 to 2022). A melanoma derived from melanocytes of the uveal tract. "High RUNX1 expression levels were linked to worse OS and DFS in CESC, COAD, GBM, KIRC, brain lower-grade glioma (LGG), and uveal melanoma (UVM), but were related to better OS and DFS in BRCA." (PMID 35534796, 2022).
age-related macular degeneration (1 paper, 2023). Age-related loss of vision in the central portion of the retina (macula), secondary to retinal degeneration. "These authors further characterized RUNX1 expression in critical cell types involved in a laser-induced murine model of Choroidal Neovascularization (CNV) and provided data supporting RUNX1 inhibition as a new potential therapy for neovascular age-related macular degeneration." (PMID 37670378, 2023).
ameloblastoma (1 paper, 2022). The most common odontogenic tumor, arising from the epithelial component of the embryonic tooth and usually affecting the molar-ramus region of the mandible or maxilla. "Our bioinformatic results confirm that many genes are involved in the pathogenesis of ameloblastoma, such as RUNX1, which had been reported as an indicator of an early epithelial lineage." (PMID 36553196, 2022).
aortic aneurysm (1 paper, 2024). A ruptured aneurysm located in the wall of the proximal portion of the descending aorta proceeding from the arch of the aorta. "Elevated SLC44A2 in aortic aneurysm is associated with upregulated runt-related transcription factor 1 (RUNX1)." (PMID 38916960, 2024). "We found that the upregulated RUNX1 in VSMCs contributed to the compensating increase in SLC44A2 during aortic aneurysm." (PMID 38916960, 2024). "Taken together, these results show that upregulation of RUNX1 in VSMCs accounts for the induction of SLC44A2 during aortic aneurysm." (PMID 38916960, 2024). "LEN inhibits VSMC phenotypic switching by modulating the RUNX1/SLC44A2 axis and improves the aortic pathology in mouse aortic aneurysm models, revealing a potential prospect for clinical application in humans." (PMID 38916960, 2024). "Lastly, LEN may upregulate RUNX1 to increase SLC44A2 expression, ameliorating VSMC phenotypic switching and protecting against aortic aneurysm." (PMID 38916960, 2024). "Additionally, lenalidomide (LEN) administration enhances SLC44A2 expression primarily through runt-related transcription factor 1 (RUNX1), leading to improvements in aortic aneurysm conditions, which provides a potential new therapeutic strategy for aortic aneurysm." (PMID 38916960, 2024).
Aortic dissection (1 paper, 2024). Aortic dissection refers to a tear in the intimal layer of the aorta causing a separation between the intima and the medial layers of the aorta. "The findings suggest that the inflammatory response mediated by aortic PVAT plays a significant role in the pathogenesis of aortic dissection, and this alteration is closely associated with RUNX1." (PMID 38693222, 2024). "Therefore, investigating the pathogenesis underlying the involvement of RUNX1 in aortic dissection holds immense significance for identifying potential therapeutic targets." (PMID 38693222, 2024). "The results of this study indicate that RUNX1 plays an important role in the pathogenesis of aortic dissection and is a potential target for disease prevention and testing." (PMID 38693222, 2024). "In this study, we have identified the involvement of RUNX1/NF-κb in the pathogenesis of aortic dissection through its regulation of PVAT-mediated inflammatory response." (PMID 38693222, 2024). "The presence of aortic dissection is accompanied by evident inflammatory alterations in the PVAT, and this phenomenon appears to be associated with the involvement of RUNX1." (PMID 38693222, 2024). "It is plausible that the regulation of PVAT's inflammatory changes by RUNX1/NF-κB signaling pathway plays a role in the pathogenesis of aortic dissection." (PMID 38693222, 2024). "This suggests that targeting PVAT inflammatory response and RUNX1 could be promising strategies for treating aortic dissection." (PMID 38693222, 2024). "In this study, the presence of inflammation and elevated levels of RUNX1 were also observed in the PVAT of individuals with aortic dissection, indicating that RUNX1 may contribute to disease pathogenesis through PVAT-mediated inflammation." (PMID 38693222, 2024). "Through clinical transformation, in the future, a variety of strategies such as small molecule inhibitors, monoclonal antibodies, gene editing technology or RNA interference may be used to target RUNX1 in the aortic PVAT for the prevention of aortic dissection." (PMID 38693222, 2024). "In addition, there is no specific test index for aortic dissection at present, and RUNX1 may become a new test index for aortic dissection in the next research." (PMID 38693222, 2024). "The mouse model of aortic dissection was established through intraperitoneal injection of AngII and BAPN in the drinking water, enabling the detection of inflammatory factors and RUNX1 expression in the aortic PVAT at different stages of aortic dissection." (PMID 38693222, 2024).
atrial fibrillation (1 paper, 2025). A disorder characterized by an electrocardiographic finding of a supraventricular arrhythmia characterized by the replacement of consistent P waves by rapid oscillations or fibrillatory waves that vary in size, shape and timing and are accompanied by an irregular ventricular response. "ECG analysis revealed a high incidence of atrial fibrillation (AF), frequent AF episodes, and prolonged mean AF duration in circNAB1(+) mice following TAC and delivery of EGR1, Gadd45b, or Runx1, comparable to control vector delivered mice." (PMID 40145839, 2025).
AV septal defects (1 paper, 2022). "In particular, gains involving RUNX1 were more frequent in subjects with AV septal defects and tetralogy of Fallot, which are endocardial cushion defects frequently observed in DS." (PMID 35356434, 2022).
Blindness (1 paper, 2020). Blindness is the condition of lacking visual perception defined as a profound reduction in visual perception. "In addition, the development of drugs targeting RUNX1 may have multiple applications in the treatment of ocular conditions leading to blindness since RUNX1 also plays a critical role in aberrant ocular angiogenesis." (PMID 33257736, 2020).
blood disease (1 paper, 2016). A disease that occurs in the blood. "An interesting example is the pair ENSG00000263264, for which very little annotative information is known, and RUNX1, a well-characterized transcription factor that has a role in the development of normal hematopoiesis and is a causative gene for blood diseases." (PMID 27048349, 2016).
bone marrow fibrosis (1 paper, 2016).
bronchiolitis (1 paper, 2023). Inflammation of the bronchioles characterized by swelling of the bronchioles and mucus accumulation. "The current study has identified that cg01680062 on RUNX1 and cg08552853 near IL1RL2 are significantly associated with bronchiolitis severity." (PMID 37679381, 2023).
calcific aortic valve disease (1 paper, 2023). "Furthermore, a previous study reported that RUNX1 is involved in the development of calcific aortic valve disease and is upregulated in human aortic valve interstitial cells treated with calcifying media." (PMID 37175670, 2023).
cartilage disorders (1 paper, 2016). "Thus, we provided in vivo data that potentially support the therapeutic efficacy of the cartilage anabolic function of Runx1 in cartilage disorders." (PMID 26728350, 2016).
chronic leukemia (1 paper, 2016). A slowly progressing leukemia characterized by a clonal (malignant) proliferation of maturing and mature myeloid cells or mature lymphocytes. "Using Partek Genomics Suite 6.6 we examined the relationship between expression of RUNX1 and RAG1/RAG2 expression in a panel of acute and chronic leukemias from the MILE study (Microarray Innovations in LEukemia), a global microarray study comprising gene expression analysis of > 4000 patients." (PMID 27056890, 2016).
Cognitive impairment (1 paper, 2023). Abnormal cognition is characterized by deficits in thinking, reasoning, or remembering. "RUNX1 belongs to master regulators for the age-dependent microglia module and increases the level of G9a through histone lysine methylation, leading to the increase of neuroinflammatory markers such as interleukin-6, tumor necrosis factor-α and then cognitive impairment in rats." (PMID 37187578, 2023).
colitis (1 paper, 2025). Inflammation of the colon. "It has been demonstrated that TRAF5 deficiency causes DDS-induced colitis; through RUNX1, TRAF5 regulates the immune response and controls the differentiation of Th1 and Th17 cells, contributing to the pathophysiology of colitis." (PMID 40093618, 2025).
congenital amegakaryocytic thrombocytopenia (1 paper, 2018). "Such a technique could therefore be applied to understanding the cells of origin in familial thrombocytopenia, or a recently described case of RUNX1-deleted Congenital Amegakaryocytic Thrombocytopenia." (PMID 29300724, 2018).
congenital cataracts (1 paper, 2023). "Patient #3 had a deletion in chromosome 21, including the RUNX1, DYRK1A, and KCNJ6 genes, classified as likely pathogenic as variants in DYRK1A have been associated with bilateral congenital cataracts." (PMID 36980880, 2023).
congenital heart malformation (1 paper, 2018). A disease that has its basis in the disruption of heart development. "Runx1 copy number variation is associated with congenital heart malformation including TOF and thus differential methylation leading to aberrant expression of this gene in TOF is significantly plausible." (PMID 30212560, 2018).
congenital myopathies (1 paper, 2023). "Runx1 is also important for the maintenance of muscle integrity as it prevents denervated myofibers from undergoing myofibrillar disorganization and autophagy, found in congenital myopathies." (PMID 37445828, 2023).
cylindromas (1 paper, 2014). "Strong nuclear staining of protein from both Notch target genes LEF1 and RUNX1 were observed in cylindromas, spiradenomas and trichoepitheliomas." (PMID 25565632, 2014).
cyst (1 paper, 2019). A sac-like closed membranous structure that may be empty or contain fluid or amorphous material. "Conversely, iKspPkd1del mice, which already developed some mild cysts at this time point, showed expression of pSTAT3 and RUNX1 in the cyst-lining epithelial cells and some of the surrounding dilated tubules." (PMID 31773180, 2019). "iKspPkd1del mice treated with PBS, instead, have not undergone injury/repair phase nor displayed overt cyst formation at this time point and showed almost no expression of pSTAT3 and RUNX1, as expected." (PMID 31773180, 2019).
cystic kidneys (1 paper, 2019). "STAT3 and RUNX1 displayed the strongest activation in cystic kidneys, as demonstrated by chromatin immunoprecipitation (ChIP) followed by qPCR." (PMID 31773180, 2019). "For two of the identified TFs, STAT3 and RUNX1, we also showed increased activity in mouse cystic kidneys, as well as altered expression in human ADPKD kidneys." (PMID 31773180, 2019). "By performing ChIP-qPCR for STAT3 and RUNX1 in ADPKD-affected kidneys, we confirmed increased transcriptional activity in cystic kidneys for these TFs." (PMID 31773180, 2019). "We then investigated whether binding of STAT3 and RUNX1 at the promoter region of their target genes is increased in cystic kidneys compared to non-cystic kidneys." (PMID 31773180, 2019).
diabetic retinopathy (1 paper, 2020). "In the present study, we found that RUNX1 was highly expressed in diabetic retinopathy, and the angiogenesis level was inhibited by silencing RUNX1." (PMID 32319515, 2020). "In the present study, we constructed a DR animal model and a model in HRMECs to investigate the relationship between p38 and RUNX1 in retinal micro-angiogenesis in diabetic retinopathy." (PMID 32319515, 2020). "In the present study, we constructed a DR animal model and a high model in HRMECs to investigate the relationship between p38 and RUNX1 in retinal micro-angiogenesis in diabetic retinopathy." (PMID 32319515, 2020). "All of these results suggested that RUNX1 was highly expressed in diabetic retinopathy." (PMID 32319515, 2020). "Taken together, these data suggested that p38 could regulate RUNX1 expression in diabetic retinopathy." (PMID 32319515, 2020). "We found that p38 could promote retinal micro-angiogenesis by up-regulating RUNX1 expression in diabetic retinopathy." (PMID 32319515, 2020). "Hence, taken together, these results suggested that p38 promoted retinal micro-angiogenesis by up-regulated RUNX1 expression in diabetic retinopathy." (PMID 32319515, 2020). "However, the relationship between p38 and RUNX1 in retinal micro-angiogenesis in diabetic retinopathy is still unknown." (PMID 32319515, 2020).
dissection (1 paper, 2024). The separation and isolation of tissues for surgical purposes, or for the analysis or study of their structures. "In comparison to the control group, the aortic dissection model group exhibited decreased expression of MMP-2 and NF-κB in PVAT, while TNF-α and RUNX1 expression increased." (PMID 38693222, 2024).
Ehlers-Danlos syndrome (1 paper, 2019). The Ehlers–Danlos syndromes (EDS) are a clinically and genetically heterogeneous group of heritable connective tissue disorders (HCTDs) characterized by joint hypermobility, skin hyperextensibility, and tissue fragility. "Other examples of Runx1-target genes that may be potentially vasculature-relevant are extracellular matrix molecules such as fibronectin, a gene with known functions in vasculature development and cancer, or Colagen 5a1 implicated in familial Ehlers-Danlos syndrome with lethal arterial events." (PMID 31343406, 2019).
endocarditis (1 paper, 2023). Inflammation of the endocardium. "Unfortunately, patient died of endocarditis before we could collect hair follicles or skin fibroblast, so germline nature of RUNX1 E223* mutation could not be verified." (PMID 36923434, 2023).
esophageal tumors (1 paper, 2020). "Besides, it has been reported that lincRNA-uc002yug. contributes to a combination of alternative splicing (AS) factors and RUNX1 to promote ESCC progression, and this suggested that RUNX1 has a tumor-suppressing role in esophageal tumors." (PMID 32662828, 2020).
food allergy (1 paper, 2021). Gastrointestinal disturbances, skin eruptions, or shock due to allergic reactions to allergens in food. "Here, our results show the association between DNAm levels with food allergy for CXCL12, CCR7, RUNX1, and CD3E." (PMID 33571165, 2021).
fungal infection (1 paper, 2024). "Of note, 70% of AML patients developed an IFD, while only 2.4% of ALL cases (1/42; with ETV6::RUNX1 fusion and under the high-risk protocol due to high measurable residual disease during induction) manifested an invasive fungal infection." (PMID 39057383, 2024).
Granuloma (1 paper, 2025). A compact, organized collection of mature mononuclear phagocytes, which may be but is not necessarily accompanied by accessory features such as necrosis. "Similar to other forms of sarcoidosis, the expression of RUNX1, MMP9, MMP12, CCR5, ITGAX, CD44, and human leukocyte antigens (HLA) is also seen in the granuloma of CS." (PMID 40521183, 2025).
granulosa cell tumor (1 paper, 2022). A slow-growing, malignant tumor, characterize by the presence of granulosa-like cells and Call-Exner bodies, that is almost always found in the ovary. "Altogether, our findings showed that loss of Runx1 in the mouse ovarian somatic cells increased the incidence of granulosa cell tumors." (PMID 36430923, 2022). "Considering this shared role between FOXL2 and RUNX1 in granulosa cell gene regulation, it is possible that Runx1 misexpression contributes to granulosa cell tumors as well." (PMID 36430923, 2022). "Runx1 KO tumors presented a diffuse growth of relatively uniform cells organized in sheets, with small eosinophilic cavities and hemorrhagic cysts, reminiscent of granulosa cell tumors." (PMID 36430923, 2022). "In Runx1 KO mice, cells composing the tumors showed an intense expression for FOXL2, indicating that the tumors were granulosa cell tumors." (PMID 36430923, 2022).
hereditary thrombocytopenia (1 paper, 2025). "Haploinsufficiency of RUNX1 leads to reduced transcriptional regulation of key genes involved in hematopoiesis, resulting in hereditary thrombocytopenia, characterized by a decreased number of circulating platelets." (PMID 41300732, 2025).